HLA-B (major histocompatibility complex, class I, B)
Diseases named in the same sentence as HLA-B in open-access papers (continued):
Sharing a sentence is not in itself a finding about the gene and the disease.
sacroiliitis (13 papers, 2015 to 2025). "The HLA-B*27:05:02 allele is positively associated with enthesitis, dactylitis, and symmetric sacroiliitis, while the HLA-B*08:01:01 and HLA-C*07:01:01 haplotype is associated with joint fusion and deformities, asymmetric sacroiliitis, and dactylitis." (PMID 40284188, 2025). "Other genotype-phenotype associations are: HLA B*08.01 with asymmetric sacroiliitis, peripheral arthritis, ankylosis and increased joint damage, whereas HLAB*27 is associated with symmetric sacroiliitis, dactylitis, and enthesitis." (PMID 36902329, 2023). "The table shows that HLA-B*27:05:02 and both of its haplotypes were strongly associated with symmetrical sacroiliitis." (PMID 25948071, 2015). "The HLA phenotypes are also associated with different clinical manifestations of PsA, whereas HLA-B*08 is associated with asymmetric sacroiliitis, peripheral arthritis ankylosis, and increased joint damage, and HLA-B*27 is associated with symmetric sacroiliitis, dactylitis, and enthesitis." (PMID 39519223, 2024). "Moreover, the HLA-B*08.01 allele has been linked to asymmetric sacroiliitis, peripheral arthritis, ankylosis and increased join damage, and HLA-B*27 with symmetric sacroiliitis, dactylitis, and enthesitis." (PMID 37628670, 2023). "Given that we also noticed an increased frequency of the HLA-B*35 allele in patients with symptoms of axSpA and without any other known cause of axSpA, we conducted a study in which we confirmed the connection between sacroiliitis detected by MRI and the HLA-B*35 allele in patients with un-axSpA." (PMID 34199710, 2021). "One hundred and thirty-one patients were ASAS-positive axial SpA: 110 patients had structural damage or sacroiliitis (SI X-ray, computed tomography (CT) scan or magnetic resonance imaging (MRI)) and 21 patients were HLA-B*27 positive associated with more than 2 others symptoms." (PMID 30177859, 2019). "Interestingly, it has been shown that synovial-based phenotypes in PsA such as joint deformities and joint fusion are associated with HLA-B*08, and similarly, sacroiliitis in PsA is most commonly associated with HLA-B*08." (PMID 29665824, 2018). "Thus, we observed a lower frequency of HLA-B*35 among patients with radiologically confirmed sacroiliitis grade ≥ 2, whereas its frequency was elevated in the cohort characterized by inflammatory biomarkers (elevated CRP or ESR)." (PMID 40806743, 2025). "For example, it may prove to be the case that whether you have HLA-B*27:05 or HLA-B*08:01 will determine whether you have symmetrical or asymmetrical sacroiliitis or whether you have a disease that is more axial or entheseal predominant, or perhaps more synovial predominant." (PMID 25948071, 2015).
dengue (12 papers, 2010 to 2025). "The overall tendency of HLA-B*44 allele suggests a protective effect against dengue [P = 2.0E-02, OR = 0.86 (0.75–0.98)]." (PMID 40303409, 2025). "The significant difference between each subgroup highlights HLA-B*44’s increased protective influence on DHF likely have influenced the overall role for the allele with respect to dengue." (PMID 40303409, 2025). "A recent study in neighbouring Malaysia which has a similar ethnic mix to Singapore identified HLA-B*13 and HLA-B*18 as being associated with dengue susceptibility and protection respectively amongst patients with Malay ethnicity." (PMID 27390842, 2016). "The role of HLA-B*35:01 in dengue is uncertain as differing associations were found in previous reports." (PMID 25659158, 2015). "Of the 36 HLA-B alleles studied, B*07, B*13, B*15, B*38 and B*40 were the most common alleles found at frequencies greater than 5% in Malay dengue patients." (PMID 20927388, 2010). "In addition, the HLA-B*14 and B*52 alleles were reported to be protective against dengue disease respectively in Cuban and Thai populations, which are probably in contrast to our present finding." (PMID 20927388, 2010). "Further, HLA-B*44 (3.1 fold decrease, P = 1 in DF, 3.1 fold decrease, P = 0.551 in DHF) allele was observed to be decreased in both dengue case groups." (PMID 20927388, 2010). "Dot plot analysis revealed that the antigen presentation markers HLA-A and HLA-B were expressed at comparable levels in monocytes from healthy controls, Dengue infection, Dengue with warning signs, and severe Dengue patients." (PMID 41012666, 2025). "HLA-A*24 and HLA-B*44 are frequently mentioned in the literature and warrant further research in a meta-analysis to determine their role in dengue immunity." (PMID 36532922, 2022). "The HLA-B alleles 07:05, 38:02 and 58:01 and HLA-DRB1* 03:01 were also reduced in the severe dengue group compared to the population background group, but these were not statistically significant after correction." (PMID 25659158, 2015). "On the other hand, HLA-B alleles 35:01 and 51:01 and HLA-DRB1* 12:02 were associated with a higher risk of developing severe dengue compared to the background population." (PMID 25659158, 2015). "Pathogenic variants of MHC molecules have been hypothesized to cause severity in dengue and hence, from the laboratory confirmed/presumptive patients, 227 were selected by their ethnicities (Malay, Chinese and Indians- excluding those with mixed parentage) for HLA-A and HLA-B typing." (PMID 24647042, 2014). "In this study we have genotyped HLA-A, HLA-B, HLA-Cw, HLA-DR, and HLA-DQ loci of 187 well-characterized dengue patients and this is the largest immunogenetic study performed in LA population reported to date." (PMID 23818909, 2013). "The HLA type of the HLA-A, HLA-B, HLA-C, HLA-DR, and HLA-DQ loci of the 187 confirmed dengue of DENV-3 genotype III was determined in low resolution." (PMID 23818909, 2013). "For an example, the allele B*07, was found to be low in mainland Southeast Asians and a study done on Thais showed that T cell responses to an HLA-B*07-restricted epitope on the dengue NS3 antigens correlate with disease severity." (PMID 20927388, 2010). "For MHC class I, HLA-A and HLA-B have been an area of focus for dengue severity research." (PMID 36532922, 2022). "When HLA-A*33:01 was analyzed for linkage disequilibrium with alleles in other loci found in this study to have a similar tendency in dengue patients (i.e., protection against severe dengue), we found that HLA-B*58:01 and HLA-DRB1*03:01 are in linkage disequilibrium with A*33:01 (data not shown)." (PMID 25659158, 2015). "Phenotype frequencies of HLA-A, HLA-B and DRB1 and their association with dengue disease severity." (PMID 25659158, 2015). "The HLA-B*44 was on the other hand reported to be protective against dengue disease in the Thais." (PMID 20927388, 2010).
dengue (continued). "Taking the total dengue cases in all the three ethnic groups, we noticed increased frequencies of HLA-B* 78 (2.4 fold rise, P = 0.09) allele in DF patients when compared to healthy controls while in the DHF group HLA-B*53 increased 2.9 fold (P = 0.042, Pc = 1.008) as compared to healthy individuals." (PMID 20927388, 2010). "Next, we analyzed transcriptional changes in HLA-A, HLA-B, ISG15, and CXCL10 across Dengue disease severity." (PMID 41012666, 2025). "Our study also found HLA-B*35:01 to be increased in the severe dengue and DSS groups, and HLA-B*51:01 to be increased in the severe dengue group compared to the background population." (PMID 25659158, 2015). "HLA-B*44 Doi plots showed minor asymmetry (hemorrhagic fever versus healthy controls) and no asymmetry (dengue versus healthy controls); there was a combined subgroup analysis Doi plot indicating no asymmetry with an LFK index of -0.64." (PMID 36532922, 2022). "Phenotype frequencies of HLA-A, HLA-B and DRB1 and their association with presence or absence of shock in severe dengue." (PMID 25659158, 2015). "However, the role of HLA-B*13 in dengue virus infection is not the same." (PMID 27760141, 2016).
enthesitis (12 papers, 2015 to 2026). Inflammation at the site of insertion of ligaments, tendons, and other fibrous structures into bone. "This association suggests that a gene other than HLA-B*27:05, such as C*01:02:01 that is present on the B*27:05-C*01:02 haplotype, drives the association with enthesitis or that a combination of genes on that haplotype confers susceptibility to enthesitis." (PMID 25948071, 2015). "Furthermore, another study found enthesitis and dactylitis were positively associated with the same MHC Class I genetic marker (i.e., the HLA-B*27:05:02)." (PMID 38472528, 2024). "Enthesitis and ESR were significantly higher in patients with HLA-B*2705 than those with B27-negative." (PMID 26273634, 2015). "The peripheral arthritis, enthesitis, and hip joint involvement in JAS with HLA-B*2704 were significantly higher than those in AAS with HLA-B*2704." (PMID 26273634, 2015).
acute myeloid leukemia (11 papers, 2019 to 2026). Acute myeloid leukemia (AML) is a group of neoplasms arising from precursor cells committed to the myeloid cell-line differentiation. "These subnetworks included hub genes such as IFIT1, PSMB9, and HLA-B, which are known to be associated with immune evasion and drug resistance in acute myeloid leukemia." (PMID 42123467, 2026). "Among these alleles, the existing literature highlights associations between aplastic anemia and HLA-B*49:01:01, acute myeloid leukemia and HLA-C*07 and childhood common acute lymphoblastic leukemia and HLA-DPB1*02:01." (PMID 39329950, 2024). "For example, HLA-C3 is associated with acute myeloid leukemia in the Korean population, HLA-B*40 is associated with acute lymphoblastic leukemia in the Mexican population, and HLA-B*40:02 is associated with acquired aplastic anemia in Japanese patients." (PMID 35626230, 2022). "Our patient was a 75-year-old female with acute myeloid leukemia who received an HLA-B antigen mismatched, unrelated peripheral blood stem cell transplant with a major ABO incompatibility (blood group A+ in the donor and blood group O+ in the recipient)." (PMID 39246802, 2024). "We investigated the potential impact of HLA-B genotypes on the efficacy of immunotherapy for relapse prevention in acute myeloid leukemia (AML)." (PMID 37597015, 2023). "Individuals with human leukocyte antigen (HLA)-A3 and HLA-B8 are underrepresented in BCR-ABL+ chronic myeloid leukemia (CML), and individuals with HLA-B*07, B*18, or B*40 have a lower risk of nucleophosmine-1 (NPM1)-mutant acute myeloid leukemia (AML)." (PMID 33086698, 2020).
multiple sclerosis (11 papers, 2007 to 2025). A progressive autoimmune disorder affecting the central nervous system resulting in demyelination. "We did however find SNPs in HLA-B and the vitamin D-binding protein were significant predictors of risk of progression to clinically definite multiple sclerosis." (PMID 35891671, 2022). "CNVs at HLA-B locus have been reported previously and many HLA genes were found to be associated with several diseases, such as multiple sclerosis." (PMID 23991104, 2013). "For instance, Epstein Barr virus and HLA-B*4402 are associated with multiple sclerosis, and HTLV-1 and HLA-B*5401 are associated with HAM/TSP." (PMID 22396638, 2012). "Several HLA genes that play a major role in the immune response (including HLA-B/C, HLA-DRB1, and HLA-DRB5) were associated with 2 or more regional volumes and simultaneously with demyelinating diseases, including multiple sclerosis, a prominent immune-mediated disorder." (PMID 39269986, 2024). "Three HLA alleles had evidence for association with depression after correcting for multiple testing (p < .004): HLA-B*08:01 and HLA-DQB1*02:01 (SLE) and HLA-DRB1*03:01 (multiple sclerosis, primary adrenocortical insufficiency, SLE)." (PMID 31570195, 2020).
sarcoidosis (11 papers, 2015 to 2025). Sarcoidosis is a multisystemic disorder of unknown cause characterized by the formation of immune granulomas in involved organs. "In our study, HLA-DRB1*15:01 and HLA-B*07:02 were also observed as risk factors for sarcoidosis at the primary significance level." (PMID 37153085, 2023). "In the HLA-B locus, 45 different variants were distinguished, and two of them, HLA-B*15:01 and B*58:01, were associated at the primary level as protective for sarcoidosis." (PMID 35661780, 2022). "Indeed, the association between HLA-B*0702 and sarcoidosis was first identified in a Japanese population; in contrast, HLA-B*07 was associated with increased risk of sarcoidosis in a Swedish population." (PMID 32826979, 2020). "A genetic variant within an HLA-B, rs2276448, was also associated with extrathoracic sarcoidosis." (PMID 31126090, 2019). "ACE (angiotensin-converting enzyme) and lysozyme levels were also determined, ruling out sarcoidosis, and HLA-B (human leukocyte antigen) was determined, confirming the presence of HLA B*07 and HLA B*15." (PMID 38592169, 2024). "Regarding clinical phenotypes of sarcoidosis, HLA-A*01:01, HLA-B*08:01, HLA-C*07:01, HLA-DRB1*03:01, HLA-DQA1*05:01, and HLA-DQB1*02:01 associated with Löfgren’s syndrome." (PMID 37153085, 2023). "The linkage of variants HLA-B*08, HLA-DRB1*03:01, and HLA-DQB1*02:01 with good prognosis of sarcoidosis was observed previously in a Croatian population." (PMID 37153085, 2023). "Another study showed HLA-B and HLA-DRB1 association with both sarcoidosis and thyroid disease." (PMID 37399514, 2023). "Taken together, we confirmed the association of rs4143332 at HLA-B and rs1800629 at TNF locus with acute onset of sarcoidosis in the Serbian sub-cohort and describe potential genetic links with several clinical features, including the recently described phenotypes of organ involvement." (PMID 37621457, 2023). "Reanalysis of a sarcoidosis scRNA-seq dataset revealed that, similar to NL and NXG, sarcoidosis lesional fibroblasts expressed high levels of MHC (e.g., HLA-B and HLA-DRA), CD74, PLOD2, STAT1, TNC, PRSS23, PSMB9, and CXCL9." (PMID 39989459, 2025). "Our eQTL/GWAS results implicating MHC Class I and II genes are quite consistent with prior candidate gene/GWAS sarcoidosis studies as we identified MHC Class I genes HLA-B and HLA-C to be well represented in EAs (compared to controls) and HLA-B primarily in AAs." (PMID 38390497, 2023).
asthma (10 papers, 2019 to 2024). "For White participants, the leucine allele at amino acid 103 within HLA-B was associated with reduced odds of being a late-onset asthma case (OR = 0.48, 95%CI: 0.30 to 0.74)." (PMID 37415598, 2023). "Indeed, our GWASs of these five dimensions’ associated genetic loci (such as HLA-B) to asthma and its constellation neighbors, such as allergic rhinitis, confirmed by matching them against the GWAS Catalog." (PMID 38177845, 2023). "HLA-C*04:01 was protective for being a late-onset asthma case (OR = 0.25, 95%CI: 0.09 to 0.70) whereas HLA-B*40:02 and HLA-DRB1*04:05 increased the odds of being a case [(OR = 3.77, 95%CI: 1.91 to 7.44; OR = 8.19, 95%CI: 2.51 to 26.79), respectively]." (PMID 37415598, 2023). "For White participants, two MHC class I alleles, HLA-B*40:02 and HLA-C*04:01, and one MHC class II allele, HLA-DRB1*04:05, were significantly associated with late-onset asthma." (PMID 37415598, 2023). "We identified eight eGenes whose eQTL colocalized with GWAS signals for pulmonary diseases, of which three, HLA-B, HLA-DQA1 and HLA-DQB1, had been previously associated with Asthma in GWAS and in the UK Biobank." (PMID 31746734, 2019). "In addition, our MAGMA analyses implicated another four pleiotropic genes—RERG, RBM6, SDK1, and HLA-B as potential targets for further investigation into asthma and GERD." (PMID 39223263, 2024). "For the HLA analysis, HLA-B*40:02 and HLA-DRB1*04:05, HLA-B*40:02, HLA-C*04:01, and HLA-DRB1*04:05, and HLA-DRB1*03:01 and HLA-DQB1 were significantly associated with late-onset asthma in all, White, and Black participants." (PMID 37415598, 2023). "On the one hand, a majority of genes in MHC region are related to immune response which may bring false positives; on the other hand, for asthma and allergy diseases, MHC region was reported as containing some of the strongest association signals such as HLA-DQB and HLA-B." (PMID 32373153, 2020). "After comparison, asthma and GERD were found to share six genes (ERBB3, RBM6, HLA-B, SDK1, RERG, RAB5B), one of which, ERBB3, was also significantly associated with both eczema and GERD." (PMID 39223263, 2024). "A recent study reported colocalizations between eQTLs for HLA-B, HLA-DQB1, HLA-DQA1, HLA-DRA, TAP1, and RNF5 in induced pluripotent stem cells with asthma GWAS SNPs." (PMID 35606880, 2022). "In contrast to our expectation, 6 asthma SNPs showed nominal association with lower eosinophil counts in the general population (rs1233578 [ZBED9], rs519973 [BCL6], rs7686660 [USP38], rs6691738 [TNFSF4], rs2507978 [HLA‐B], rs3117098 [HCG23]), and 1 SNP in the asthma population (rs2786098 [CRB1])." (PMID 37186423, 2023).
Hypertension (10 papers, 2018 to 2024). The presence of chronic increased pressure in the systemic arterial system. "Variants of the HLA-B gene that are associated with the risk of hypertension based on hyper-inflammatory status have been found and are related to disease-causing pulmonary hypertension caused by thrombosis." (PMID 36233190, 2022). "For example, a very well-studied polymorphism, rs9378249 upstream of the HLA-B gene, has previously been associated with bipolar disorder and hypertension." (PMID 30219098, 2018). "During the process of long-term hypertension, the myocardial inflammation response is enhanced, which in turn activates the HLA immune system, resulting in increased HLA-B expression." (PMID 38728374, 2024). "In the present study, adopting a bioinformatics approach and confirming our findings on a small cohort of hypertensive patients, we found that HLA-B and TIMP1 genes are associated with hypertension-related ventricular remodeling." (PMID 38728374, 2024). "This suggests that HLA-B mRNA expression levels have a relationship with hypertension in SARS-CoV-2-infected individuals." (PMID 38674456, 2024). "In conclusion, our study evaluated the ability of HLA-B and TIMP1 to participate in ventricular remodeling caused by hypertension." (PMID 38728374, 2024). "HLA-B was significantly overexpressed in leukocytes of patients with hypertension-induced ventricular remodeling." (PMID 38728374, 2024). "The genetic polymorphisms of the CACNA1D, HLAB, CYP11B1, and LSP1 gene regions showed significant association with hypertension." (PMID 36233190, 2022). "Additionally, genotypes HLA-A*24:02-A*24:02 and HLA-B*46:01-B*46:01 were significantly associated with stroke, while genotypes HLA-B*46:01-*46:01 and DPA1*01:03-DPA1*01:03 as well as DPB1*02:01-DPB1*05:01 were correlated with hypertension." (PMID 37841270, 2023). "HLA-B*46:01-*46:01 (0% vs. 91%, P value = 0.013), DPA1*01:03-*01:03 (7.9% vs. 3.8%, P value = 0.012), and DPB1*02:01-*05:01 (12.0% vs. 20.3%, P value = 0.028) were significantly associated with hypertension." (PMID 35321340, 2022). "Thus, HLA-B*35 could represent a marker for severe hypertension in renal disease." (PMID 37686189, 2023). "However, HLA-B mRNA expression levels were significantly higher in individuals with no comorbidities than hypertension (p = 0.0487)." (PMID 38674456, 2024).